TIGIT (T cell immunoreceptor with Ig and ITIM domains)
Diseases named in the same sentence as TIGIT in open-access papers (continued):
Sharing a sentence is not in itself a finding about the gene and the disease.
HIV-1 infection (15 papers, 2017 to 2025). The type species of lentivirus and the etiologic agent of acquired immunodeficiency syndrome (AIDS). "An upregulated expression of various ICMs including PD-1, CTLA-4, TIM-3, LAG-3, and TIGIT has been reported in HIV-1 infection." (PMID 40872312, 2025). "NK cells including TIGIT+NK and TIGIT−NK cells showed significantly increased Ki67 expression in all HIV-1 infection status compared to HIV-1-negative donors (all P < 0.05)." (PMID 33717085, 2021). "In this study, we analyzed and compared the characteristics of TIGIT+ and TIGIT− NK cells at different stages of HIV-1 infection." (PMID 33717085, 2021). "No significant change in the expression of TIGIT and PD-1 was observed at any time after HIV-1 infection compared to preinfection, although a trend toward increased TIGIT was detected at early chronic infection (P = 0.06)." (PMID 34753817, 2021). "The phenotype and function of TIGIT+NK cells analyzed appear to be ineffective in controlling HIV-1 infection." (PMID 33717085, 2021). "Overall NK cells, including TIGIT−NK and TIGIT+NK cells, secreted lower CD107a in the first month of acute HIV-1 infection than in chronic HIV-1 infection over 2 years and HIV-1-negative donors (all P < 0.05)." (PMID 33717085, 2021). "Contrary to the upregulated TIGIT expression on NK cells, CD96, which shares the ligand of CD155 with CD226 and TIGIT, was upregulated on NK cells in both acute and chronic HIV-1 infection." (PMID 33717085, 2021). "Here, 19 acutely infected HIV-1 patients traced at first, third and twelfth month, and age-matched patients with chronic HIV-1 infection were enrolled to investigate the phenotype and functions of TIGIT expression on NK cells." (PMID 33717085, 2021). "Cytokines such as TNF-α and IFN-γ secreted by NK cells, including TIGIT−NK cells and TIGIT+NK cells, decreased in the first, twelfth month of HIV-1 infection compared with HIV-1-negative donors." (PMID 33717085, 2021). "We focused this review on the T cell immunoreceptor with immunoglobulin and ITIM domains (TIGIT) immune checkpoint receptor as expression of TIGIT, its competitors, and its ligands are broadly dysregulated on multiple cell types in HIV-1 infection." (PMID 32432050, 2020). "In the setting of active HIV-1 infection, TIGIT expression is increased on subsets of NK cells coexpressing DNAM-1." (PMID 32432050, 2020). "Although TIGIT blockade can rescue NK cell function against cancer, further evidence illustrating the potential benefits of targeting the TIGIT axis in the context of HIV-1 infection is needed." (PMID 32432050, 2020). "Increased expression of TIGIT during HIV-1 infection was coupled to a transitional T-betdimEomeshi transcriptional phenotype and decreased functional capacity of HIV-specific CD8+ T cells." (PMID 28084312, 2017). "Based on our previous results, we next sought to determine whether maturation of adaptive NKG2C+ NK cells and TIGIT expression were affected during HIV-1 infection in vivo." (PMID 40473838, 2025). "Moreover, TIGIT expression is accumulated in mature adaptive NKG2C+ CD57 + NK cells from women with chronic HIV-1 infection." (PMID 40473838, 2025). "In addition to displaying a TEMRA-like phenotype, Vδ1 T cells had elevated expression of CD160, TIGIT, and PD-1 indicative of in vivo activation occurring during the course of HIV-1 infection." (PMID 39149467, 2024). "Similarly, we found rapid increases of KLRG1, LAG-3, PD-1, and TIGIT expression in blood and tissue NK cells within 2 weeks after HIV-1 infection." (PMID 36282589, 2022). "Then early activation of TIGIT+NK and TIGIT−NK cells may lead to the depletion of CD4 T cells in acute and chronic HIV-1 infection, especially in the first month of infection (TIGIT+NK: r = −0.72, P = 0.001; TIGIT−NK: r = −0.66, P = 0.004)." (PMID 33717085, 2021). "Therefore, large clinical samples would be needed to clarify the functions of TIGIT expression on NK cells during HIV-1 infection." (PMID 33717085, 2021).
HIV-1 infection (continued). "In chronic HIV-1 infection, CD8 T-cell exhaustion is linked to an intermediate transcriptional phenotype expressing high levels of Eomesodermin (Eomes) that is directly linked to co-expression of PD-1 and TIGIT." (PMID 34712231, 2021). "Furthermore, in including the first and third months of acute HIV-1 infection, more NK cells expressed TIGIT, fewer NK cells released TNF-α, and there was a lower MFI of TNF-α expressed by NK cells, especially in the third month of infection." (PMID 33717085, 2021). "TIGIT expression on natural killer (NK) cells is associated with dysfunction during chronic HIV infection, but the phenotype and biological functions of these cells in the context of acute HIV-1 infection remain poorly understood." (PMID 33717085, 2021). "Expression of TIGIT on CD8+ T cells and NK cells suggests that TIGIT-specific mAb therapy could synergistically unleash both types of antiviral effector cells to more robustly target active HIV-1 infection." (PMID 32432050, 2020). "As NK cell and CD8+ T cell expression of TIGIT increases with acute HIV-1 infection, introducing mAb therapy to overcome the higher affinity TIGIT/PVR inhibitory interaction in favor of DNAM-1/PVR-mediated activation is a rational strategy to address lingering HIV-1 infection." (PMID 32432050, 2020). "As TIGIT MFI on HIV-specific cells was markedly higher in chronic untreated HIV-1 infection and discriminated HIV-specific from CMV-specific cells, we next investigated if the intensity of TIGIT expression on CD8+ T cells was associated with their functional capacity." (PMID 28084312, 2017). "Synergistic upregulation of PD-1 and TIGIT is linked to increased inhibitory function, poor functionality of HIV-1 specific T-cell responses and is inversely correlated with CD4% and CD4/CD8 ration in HIV-1 infection, suggesting that this population resembles highly exhausted CD8 T-cells." (PMID 34712231, 2021). "However, we also found increased CD38/HLA-DR coexpression on the surface of NK cells, including TIGIT+NK and TIGIT−NK cells, in the first, third and twelfth month of HIV-1 infection and in chronic infection over 2 years compared to healthy controls (all P < 0.0001)." (PMID 33717085, 2021). "We previously showed that TIGIT also marks CD8 + T cells unable to respond to MDDC stimulation and the fate of these cells in vivo during HIV-1 infection and in response to anti-TIGIT antibodies should be assessed in the future." (PMID 40473838, 2025). "Increasing TIGIT-mediated inhibition of CD8 T-cells and parallel downregulation of CD226 has been reported in HIV-1 infection despite early initiation of antiretroviral therapy (ART)." (PMID 34712231, 2021). "Although CD155, as the ligand of TIGIT, CD226 and CD96, is rarely expressed on CD4 T cells, it was upregulated in acute and chronic HIV-1 infection." (PMID 33717085, 2021). "TIGIT and CD226 coexpression on NK cells was downregulated until in chronic HIV-1 infection over 2 years, though it is insignificant (P = 0.053)." (PMID 33717085, 2021). "Concurrent levels of the exhaustion markers PD-1 and TIGIT were elevated, suggesting that the CD161+ CD4+ T cells are already exhausted during the course of HIV-1 infection as early as the viral set point, approximately one month post-infection." (PMID 33322496, 2020). "In this study, CD96−CD226+ cells in total NK cells including TIGIT+NK and TIGIT−NK cells significantly diminished, while CD96+CD226− cells expanded at all the acute and chronic phases of HIV-1 infection, which indicated that the expression of these two NK subset cells were oppositely affected." (PMID 33717085, 2021). "Contrary to NK cell activation aggravated by TIGIT expression in acute and chronic HIV-1 infection, TIGIT did not enhance NK cell proliferation." (PMID 33717085, 2021). "Our data showed an increase in the frequency of TIGIT+NK cells were found in over 2 years of chronic HIV-1 infection but not in acute infection or even in early chronic infection." (PMID 33717085, 2021).
HIV-1 infection (continued). "Though many studies have investigated TIGIT expression and function in T lymphocytes, current understanding of TIGIT expression and function in NK cells, especially in acute HIV-1 infection (AHI) is lacking." (PMID 33717085, 2021). "Compared with healthy donors, proportionally increased TIGIT expression on NK cell subpopulations, including NKG2A+NK cells, NKG2C+NK cells, NKG2A+NKG2C−NK cells and NKG2A−NKG2C+NK cells was only observed in chronic HIV-1 infection over 2 years (all P < 0.05)." (PMID 33717085, 2021). "Of these, NKG2A−NKG2C+NK cells are not conducive to suppressing HIV-1 replication in acute HIV-1 infection, partly because the levels of TIGIT expressed on these adaptive NKG2A−NKG2C+NK cells were far higher than that on NKG2A+NKG2C−NK cells." (PMID 33717085, 2021). "While the current results suggest that successful treatment of HIV-1 result in normalized levels of activated and exhausted CD8 T-cells, we have in another cohort found that memory CD8 T-cells expressing TIGIT, PD1, CD160 and 2B4 are increased in treated HIV-1 infection as compared to seronegative." (PMID 34712231, 2021). "Compared with healthy individuals, TIGIT expression on CD3−CD56+NK cells significantly increased in chronic HIV-1 infection over 2 years (P = 0.0002) but not in the first, third, or twelfth month after the onset of HIV-1 infection." (PMID 33717085, 2021). "We found that TIGIT-expressing NK cells did not increase in frequency in the first, third and twelfth month of infection until chronic HIV-1 infection lasted over 2 years." (PMID 33717085, 2021). "In this study, we demonstrated the dynamics of TIGIT, CD96 and CD226 expression and functions in NK cells in the first, third and twelfth month after HIV-1 infection in our Beijing PRIMO clinical cohort and chronic HIV-1 individuals with over 2 years of infection." (PMID 33717085, 2021). "Expression of TIGIT is broadly dysregulated on both CD8+ T cells and NK cells in HIV-1 infection." (PMID 32432050, 2020). "Secondly, there is evidence that HIV-1 infection of CD4+ T cells induces upregulation of PVR expression and that the latent HIV reservoir is to some extent concentrated in CD4+ T cells expressing PVR and/or TIGIT." (PMID 32432050, 2020). "PD-1, CTLA-4, TIM-3, LAG-3 and, TIGIT on both CD4+ and CD8+ T-lymphocytes in the peripheral blood of treatment-naïve individuals from four cohorts, including active pulmonary tuberculosis (TB), HIV-1 infection only, HIV-TB co-infected, and healthy volunteers from North India." (PMID 40872312, 2025). "(2016) found that during untreated HIV-1 infection, T-cells expressing HIV-1 RNA and Gag protein were enriched particularly in T-cells expressing PD-1 and Tfh cell markers (PD-1+CXCR5+), with additional enrichment in cells co-expressing PD-1 with other immune checkpoint markers (TIGIT+ and CTLA-4+)." (PMID 36776833, 2023). "Additionally, the trifunctionality of TIGIT+NK and TIGIT−NK cells in secreting CD107a, TNF-α and IFN-γ might be decreased in both acute and chronic HIV-1 infection." (PMID 33717085, 2021).
Sepsis (15 papers, 2021 to 2025). Sepsis is defined as life-threatening organ dysfunction caused by a dysregulated host response to infection. "Targeting the IL-33/ST2 axis, implicated in enhancing TIGIT+ Treg suppressive function during late sepsis, represents another potential strategy." (PMID 40806563, 2025). "And the phenotypes of TIGIT-deficient (TIGIT-/-) and wild-type (WT) mice were evaluated to explore the engagement of TIGIT in the acute phase of sepsis." (PMID 38545097, 2024). "To access the impact of TIGIT deficiency on acute sepsis, we employed wild-type (WT) or TIGIT-/- mice for CLP." (PMID 38545097, 2024). "In this research, TIGIT genetic deficient mice were employed for the first time in CLP-induced sepsis model." (PMID 38545097, 2024). "Targeting the TIGIT+ Treg pathway is being explored as a therapeutic avenue to restore immune function in sepsis survivors, although the risk of triggering excessive inflammation must be carefully managed." (PMID 39594987, 2024). "To conclude, we report that TIGIT and CD155 are upregulated in acute sepsis and the elevated expression of TIGIT is associated with T cell activated and proinflammatory profiles." (PMID 38545097, 2024). "Collectively, these data reveal that anti-TIGIT treatment during CA sepsis was associated with a reversal of immune cell loss and a decrease in the frequency of PD-1+ Treg and Teff in hosts with preexisting malignancy." (PMID 34100383, 2021). "Additionally, TIGIT, an inhibitory receptor with Ig and ITIM domains, is predominantly expressed on T cells and NK cells; high expression of TIGIT has also been associated with immune dysfunction in sepsis." (PMID 40364841, 2025). "As a result, TIGIT deficiency or blockade protected mice from sepsis." (PMID 38545097, 2024). "Previous studies have found that co-inhibitory molecules, such as PD-1, CTLA-4, LAG-3, VISTA, are upregulated during sepsis, we then queried the expression of TIGIT and its ligand CD155 upon sepsis insult." (PMID 38545097, 2024). "To further elucidate how TIGIT deficiency reduced organ damage and bacterial load in CLP-induced sepsis, we assessed the proliferation and effector function of splenic T cells and NK cells from septic mice." (PMID 38545097, 2024). "Our data uncovered that both of TIGIT-/- mice and anti-TIGIT-treated mice were protected from CLP-induced sepsis as evidenced by lower bacterial load in PF and milder organ damage." (PMID 38545097, 2024). "Next, we utilized public RNA-seq dataset (GSE216902) to find out the relationship between TIGIT mRNA expression and cytokine level in sepsis patients of acute phase." (PMID 38545097, 2024). "Loss of TIGIT augments CD4+ T cell proliferative and effector competence in bacteria clearance and thus confers protection in sepsis." (PMID 38545097, 2024). "Here, we found that CD155 expression on CD11c+ cells were also induced, indicating a potential role of TIGIT signaling pathway on the development of sepsis immunosuppression regulated by T cells." (PMID 38545097, 2024). "Since sepsis mice exhibited elevated level of TIGIT in T cells, we tried to figure out the differences in effector cytokine level between TIGIT+ and TIGIT- T cells." (PMID 38545097, 2024). "CD4+ T cell immunity against polymicrobial infection during CLP-induced sepsis was enhanced by genetic ablation or antibody blockade of TIGIT." (PMID 38545097, 2024). "It has been shown that TIGIT contributes to the development of sepsis in the context of preexisting malignancy, and a similar survival benefit of TIGIT blockade was also seen as results of lymphopenia reversion." (PMID 38545097, 2024). "The pretreatment with anti-TIGIT Ab prevented CLP-induced sepsis based on a significant decrease in clinical severity score." (PMID 38545097, 2024). "TIGIT deficiency enhanced CD4+ T cell effector function and facilitated bacterial clearance during CLP induced-sepsis, resulting in decreased organ injury." (PMID 38545097, 2024).
Sepsis (continued). "Taken together, these findings proved that TIGIT blockade promoted T cell cytokine production and mobilized innate immunity during sepsis." (PMID 38545097, 2024). "Taken together, these data uncovered that TIGIT was predominantly upregulated on CD4+ T cells, CD8+ T cells and NK cells and increased TIGIT suppressed T cell function at the initiated stage of sepsis." (PMID 38545097, 2024). "In sepsis, the expansion of TIGIT+ Treg are related to post sepsis immunosuppression, while anti-TIGIT antibody treatment improved survival in cancer mice with sepsis." (PMID 38545097, 2024). "Our previous study showed that the anti-TIGIT Ab reversed sepsis-induced T-cell apoptosis in cancer septic mice and resulted in a significant survival benefit." (PMID 38114466, 2023). "Here, we identified a critical role of the coinhibitory molecule T cell Ig and ITIM domain (TIGIT) in regulating sepsis mortality." (PMID 33682797, 2021). "Because TIGIT is significantly upregulated on memory T cells, we developed a “memory mouse” model to study the role of TIGIT during sepsis in a more physiologically relevant context." (PMID 33682797, 2021). "In the current study, we found that sepsis induced TIGIT upregulation on immune cells both in PH mice and in the setting of preexisting malignancy." (PMID 34100383, 2021). "In the present study, we demonstrate fundamental differences in the role of TIGIT coinhibitory signaling during sepsis in previously naive versus immunologically experienced murine hosts." (PMID 33682797, 2021). "We then interrogated the role of TIGIT signaling on memory T cells and explored the differential effects of αTIGIT on memory versus previously naive mice during sepsis." (PMID 33682797, 2021). "In contrast, TIGIT expression was increased on bulk CD8+ T cells in memory mice compared with previously naive mice during sepsis (2.9% ± 0.6% vs. 5.3% ± 0.6%, P = 0.028)." (PMID 33682797, 2021). "We found that sepsis induced TIGIT upregulation predominantly on Tregs and NK cells in both PH and CA mice." (PMID 34100383, 2021). "Consistent with a previous report, our data demonstrated that TIGIT was upregulated on memory T cells both before and during sepsis." (PMID 33682797, 2021). "Our previous study showed that TIGIT expression on T and NK cells was upregulated in the mouse model of sepsis (our unpublished observations)." (PMID 33682797, 2021). "In sum, we found that anti-TIGIT Ab reversed sepsis-induced T cell apoptosis in CA septic mice and led to a significant survival benefit, suggesting its use as a potential immunotherapy to improve outcomes in septic patients with cancer." (PMID 34100383, 2021). "Here, we aimed to study the role of TIGIT signaling during sepsis in both PH mice and mice with preexisting malignancy." (PMID 34100383, 2021). "Furthermore, targeting TIGIT, potentially through anti-TIGIT therapy, is suggested as a promising strategy for treating immunosuppressive late-stage sepsis, leveraging its role in enhancing Treg stability and function." (PMID 40806563, 2025). "Collectively, current evidence indicates that TIM-3 primarily functions through Tregs to limit excessive inflammation during sepsis, whereas CTLA-4, LAG-3, and TIGIT are more strongly associated with the immunosuppressive state that emerges in the later stages of the disease." (PMID 40806563, 2025). "TIGIT modulates CD4+ T cell response against polymicrobial sepsis, suggesting that TIGIT could serve as a potential therapeutic target for sepsis." (PMID 38545097, 2024). "Since previous studies has proved that TIGIT blocking treatment after CLP failed to improve survival and organ damage in septic mice with naïve background, we next wanted to explore whether TIGIT blockade prior to CLP insult has effect on sepsis." (PMID 38545097, 2024). "Collectively, our data suggest that TIGIT blockade attenuates organ damage and infection in sepsis." (PMID 38545097, 2024).